STARD3NL (STARD3 N-terminal like)
Description:
Tethering protein that creates contact site between the endoplasmic reticulum and late endosomes: localizes to late endosome membranes and contacts the endoplasmic reticulum via interaction with VAPA and VAPB.
Synonyms: MENTHO; MGC3251
Tractability: Antibody: UniProt predicts a signal peptide or a membrane-spanning region. PROTAC: ubiquitination databases record sites on it; its protein half-life has been measured.
Gene: Protein-coding gene on chromosome 7 (38,178,245 to 38,230,671, forward strand). Ensembl gene ENSG00000010270.
Subcellular location: Late endosome membrane
Subcellular location (Human Protein Atlas): Vesicles
Pathways (Reactome):
Metabolism: Pregnenolone biosynthesis
Gene Ontology:
Molecular function: cholesterol binding; protein binding; protein homodimerization activity
Biological process: cholesterol transport
Cellular component: endoplasmic reticulum membrane; endoplasmic reticulum-endosome membrane contact site; endosome; late endosome membrane; lysosomal membrane; membrane; organelle membrane contact site; cytosol
Genetic constraint (gnomAD): Loss-of-function variants: 12 observed, 26.14 expected, observed/expected ratio (o/e) 0.46, 90% interval 0.29 to 0.74. The upper end of that interval is the gene's LOEUF score, 0.74, which puts it in group 3 of 6, group 1 being the genes least tolerant of losing a copy. Missense variants: 205 observed, 260 expected, observed/expected ratio (o/e) 0.79, 90% interval 0.7 to 0.88. Synonymous variants: 102 observed, 94.83 expected, observed/expected ratio (o/e) 1.08, 90% interval 0.92 to 1.27.
Homologues: Orthologues: chimpanzee STARD3NL (100% identical), macaque STARD3NL (100% identical), pig STARD3NL (97% identical), dog STARD3NL (97% identical), rabbit STARD3NL (96% identical), rat Stard3nl (96% identical), mouse Stard3nl (95% identical), guinea pig STARD3NL (95% identical), tropical clawed frog stard3nl (68% identical), zebrafish stard3nl (66% identical), Drosophila melanogaster Start1 (38% identical), Caenorhabditis elegans tag-340 (27% identical), and 1 more. Paralogues in human: STARD3 (59% identical), STAR (12% identical), STARD5 (7% identical), STARD4 (6% identical), STARD6 (6% identical).
Diseases named in the same sentence as STARD3NL in open-access papers:
STARD3NL is named in the same sentence as 7 diseases in open-access papers, as found by Europe PMC text mining. Sharing a sentence is not in itself a finding about the gene and the disease. The quoted sentences say what the papers report.
osteoporosis (3 papers, 2011 to 2022). A condition of reduced bone mass, with decreased cortical thickness and a decrease in the number and size of the trabeculae of cancellous bone (but normal chemical composition), resulting in increased fracture incidence. "Our data suggest a novel mechanistic insight into the association of Stard3nl with osteogenic differentiation and also reveal a promising therapeutic target for osteoporosis." (PMID 35098646, 2022). "Despite the fact that extensive studies on the regulatory roles of Stard3nl in bone development have been proposed based on GWAS results from patients with osteoporosis, how Stard3nl functions in modulating osteoblasts and associated bone formation remain obscure." (PMID 35098646, 2022). "Considering that inhibition of Stard3nl promoted the osteoblast differentiation, we asked whether inhibition of Stard3nl in vivo could alleviate bone loss in osteoporosis." (PMID 35098646, 2022). "Furthermore, silencing of Stard3nl in vivo reversed bone loss in OVX‐induced osteoporosis." (PMID 35098646, 2022).
Batten disease (1 paper, 2025). "A recent paper exploring the proteomic changes in microglia with another LSD, Batten disease caused by loss of CLN3, identify similar changes to those seen here, including increased TTYH3, PTTG1IP, LAMTOR3, PSAP, STARD3NL, TSPAN7, TMEM192 and NPC1." (PMID 40608809, 2025).
Niemann–Pick type C disease (1 paper, 2025). "MLN64 has a partner protein termed MENTHO (MLN64 N-terminal homolog, also termed StarD3NL); both are late endosomal proteins that co-localize with the NPC proteins associated with Niemann–Pick type C disease." (PMID 39773408, 2025).
postmenopausal osteoporosis (1 paper, 2022). Metabolic disorder associated with fractures of the femoral neck, vertebrae, and distal forearm. "Given that Stard3nl negatively regulates osteogenic differentiation, SNPs in the STARD3NL may have association with alterations in osteoblast activity that might play a role in the development of postmenopausal osteoporosis." (PMID 35098646, 2022).
STARD3NL also shares sentences with these, for which no sentence is quoted: colorectal cancer (1 paper); thalassemia (1); tumor (1).